SEMG2 (semenogelin 2)
Description:
Participates in the formation of a gel matrix (sperm coagulum) entrapping the accessory gland secretions and ejaculated spermatozoa.
Synonyms: SGII
Tractability: Antibody: UniProt places it where antibodies can reach, with medium confidence; UniProt predicts a signal peptide or a membrane-spanning region; its Gene Ontology location is reachable by antibodies, with medium confidence.
Gene: Protein-coding gene on chromosome 20 (45,221,373 to 45,224,458, forward strand). Ensembl gene ENSG00000124157.
Subcellular location: Secreted
Gene Ontology:
Molecular function: protease binding; protein binding; zinc ion binding
Biological process: antibacterial humoral response; coagulation; positive regulation of serine-type endopeptidase activity; sperm capacitation; negative regulation of flagellated sperm motility
Cellular component: extracellular exosome; extracellular region; nucleus; acrosomal vesicle
Genetic constraint (gnomAD): Loss-of-function variants: 3 observed, 8.45 expected, observed/expected ratio (o/e) 0.35, 90% interval 0.16 to 0.92. That is too few expected variants to judge how well the gene tolerates losing a copy. Missense variants: 721 observed, 691.31 expected, observed/expected ratio (o/e) 1.04, 90% interval 0.98 to 1.11. Synonymous variants: 249 observed, 237.59 expected, observed/expected ratio (o/e) 1.05, 90% interval 0.94 to 1.16.
Homologues: Orthologues: chimpanzee SEMG2 (96% identical), macaque SEMG2 (80% identical), rat Semg1 (13% identical), mouse Semg1 (13% identical), rat Svs3a (10% identical), rat Svs3b (10% identical), mouse Svs3b (9% identical), mouse Svs3a (9% identical). Paralogues in human: SEMG1 (62% identical).
Diseases named in the same sentence as SEMG2 in open-access papers:
SEMG2 is named in the same sentence as 16 diseases in open-access papers, as found by Europe PMC text mining. Sharing a sentence is not in itself a finding about the gene and the disease. The quoted sentences say what the papers report.
Infertility (5 papers, 2020 to 2024). "This protein degrades SEMG1 and SEMG2 during the transfer of spermatozoa to the female reproductive tract, and its inactivation in seminal plasma could be linked to infertility." (PMID 38654926, 2024). "In the present study, proteomic profile of seminal plasma showed both SEMG1 and SEMG2 were underexpressed in primary and secondary infertile men compared to control group." (PMID 32372034, 2020). "Western blot validation showed overexpression of ANXA2 and CDC42, and underexpression of SEMG2 proteins in primary infertility; and overexpression of ANXA2 and APP proteins in secondary infertility." (PMID 32372034, 2020). "Increased seminal plasma levels of SEMG1 and SEMG2 have been reported in men with infertility." (PMID 38654926, 2024). "Both SEMG1 and SEMG2 have been reported to be downregulated in infertile men." (PMID 38028760, 2023). "Validation of key proteins suggests that ANXA2 can be a screening biomarker for both primary and secondary infertility, whereas CDC42 and SEMG2 can be useful candidate biomarkers for primary infertility and APP for secondary infertility." (PMID 32372034, 2020).
prostate carcinoma (3 papers, 2020 to 2024). A carcinoma that arises from epithelial cells of the prostate gland. "Genes in peptidase activity pathways, including SEMG1 and SEMG2, were significantly upregulated in prostate cancer from AA men." (PMID 38566104, 2024).
small cell lung carcinoma (2 papers, 2015 to 2020). Small cell lung cancer (SCLC) is a highly aggressive malignant neoplasm, accounting for 10-15% of lung cancer cases, characterized byrapid growth, and early metastasis. "Besides, SEMG1 and SEMG2 were detected in various malignancies including small cell lung cancer (SCLC)." (PMID 33101710, 2020).
breast carcinoma (1 paper, 2020). "To extend our observations, we examined for MMP two additional breast cancer cell lines, MDA-MB-468 (Fig. 4A_Suppl) and MCF7 (Fig. 5A_Suppl), transiently transfected with SEMG1 or SEMG2 vectors." (PMID 33311447, 2020). "Moreover, we also examined MDA-MB-468 and MCF7 breast cancer cell lines transiently transfected with either SEMG1, SEMG2, or an empty vector as control for the ROS production." (PMID 33311447, 2020).
lung adenocarcinoma (1 paper, 2020). A carcinoma that arises from the lung and is characterized by the presence of malignant glandular epithelial cells. "Collectively, our data suggest tumor suppressive properties of SEMG1 and SEMG2 in model H1299 lung adenocarcinoma cells." (PMID 33101710, 2020). "To investigate the biological effects of SEMGs in lung adenocarcinoma cell model, we have generated lentiviral-transduced H1299 cells with stable overexpression of SEMG1, SEMG2 or the corresponding vehicle as control." (PMID 33101710, 2020).
lung carcinoma (1 paper, 2020). "High levels of SEMG1 and SEMG2 expression are detected in prostate, renal, and lung cancer as well as hemoblastosis." (PMID 33311447, 2020). "Both SEMGs are expressed in all types of lung cancer cell lines tested but the mRNA level of SEMG1 in general was higher than that of SEMG2." (PMID 33311447, 2020).
squamous cell carcinoma (1 paper, 2020). A carcinoma arising from squamous epithelial cells. "To expand our knowledge on SEMGs expression in NSCLCs on the protein level, we decided to check the presence of highly homologous SEMG1 and SEMG2 proteins in the panel of 5 adenocarcinoma and 1 squamous cell carcinoma NSCLC cell lines." (PMID 33101710, 2020). "However, we demonstrate here the ubiquitous presence of SEMG2 in all NSCLC cell lines tested whereas SEMG1 was detected in three out of five cell lines: in H520 squamous carcinoma and in two adenocarcinoma (H522 and H1650) cell lines." (PMID 33101710, 2020).
varicocele (1 paper, 2015). A condition characterized by the dilated tortuous veins of the spermatic cord with a marked left-sided predominance. "Some of the more abundant proteins in the unilateral varicocele group were lactotransferrin isoform 1 precursor (LTF), fibronectin isoform 3 preprotein (FN1), semenogelin-2 precursor (SEMG2), A-kinase anchor protein 4 isoform 2 (AKAP4), and semenogelin-1 preprotein (SEMG1)." (PMID 25890347, 2015).
tumor (3 papers, 2020 to 2021). "In this case, an inverse correlation between SEMG2 expression and the tumor score on the Gleason scale is noted, which indicates the association of SEMG2 with more differentiated tumors." (PMID 33966049, 2021). "The mRNA levels of SEMG1 and SEMG2 in tumor samples were higher than in peritumoral tissues." (PMID 33311447, 2020).
adenocarcinoma (2 papers, 2020). A common cancer characterized by the presence of malignant glandular cells. "Interestingly, SEMG2 displayed nuclear dot-like localization in H1299 and H1650 adenocarcinoma cells." (PMID 33101710, 2020). "Nevertheless, at least in our adenocarcinoma cancer cell model, we have shown that overexpression of both SEMG1 and SEMG2 elevated ROS production two-fold." (PMID 33101710, 2020). "SEMG1 and SEMG2 were expressed in H520 adenocarcinoma cell lines but not in normal human fibroblasts." (PMID 33311447, 2020).
cancer (2 papers, 2020). A tumor composed of atypical neoplastic, often pleomorphic cells that invade other tissues. "In the present work, we have shown that SEMG1 and SEMG2 are observed at different frequencies in various human cancer cell lines and are associated with poor prognosis for survival of patients." (PMID 33311447, 2020). "Since both SEMG1 and SEMG2 affected the activity of crucial metabolic enzymes of glycolysis, we next decided to assess whether these proteins can regulate the cancer-related metabolism because glycolysis is a well-known hallmark of cancer." (PMID 33311447, 2020). "Taken together, these data clearly demonstrate that SEMG1 and SEMG2 enhance energy metabolism of cancer cells." (PMID 33311447, 2020). "Taken together, our data demonstrate that two autosomal CTAs, SEMG1 and SEMG2, are frequently expressed in human malignancies and enhance energy metabolism of cancer cells." (PMID 33311447, 2020). "Taken together, these results suggest that both SEMG1 and SEMG2 enhance the fluorescence intensity of MitoTracker, hence reflecting an increase of MMP and possible cancer aggressiveness." (PMID 33311447, 2020). "To assess in details the influence of SEMGs on energy metabolism of cancer cells we have carried out the SeaHorse profiling of Mia-Paca2 cell line overexpressing SEMG1, SEMG2, or control vector." (PMID 33311447, 2020).
SEMG2 also shares sentences with these, for which no sentence is quoted: osteosarcoma (1 paper); ovarian carcinoma (1); pancreatic adenocarcinoma (1); pancreatic cancer (1); postherpetic neuralgia (1).